FBXL4 (F-box and leucine rich repeat protein 4)
Description:
Substrate-recognition component of the mitochondria-localized SCF-FBXL4 ubiquitin E3 ligase complex that plays a role in the restriction of mitophagy by controlling the degradation of BNIP3 and NIX mitophagy receptors. Rescues also mitochondrial injury through reverting hyperactivation of DRP1-mediated mitochondrial fission (By similarity).
Synonyms: FBL4; FBL5; MTDPS13
Tractability: PROTAC: ubiquitination databases record sites on it; its protein half-life has been measured.
Gene: Protein-coding gene on chromosome 6 (98,868,535 to 98,948,006, reverse strand). Ensembl gene ENSG00000112234.
Subcellular location: Cytoplasm; Nucleus; Mitochondrion outer membrane
Subcellular location (Human Protein Atlas): Nuclear speckles
Pathways (Reactome):
Immune System: Antigen processing: Ubiquitination & Proteasome degradation
Metabolism of proteins: Neddylation
Gene Ontology:
Molecular function: protein binding; ubiquitin-like ligase-substrate adaptor activity
Biological process: autophagy of mitochondrion; negative regulation of mitophagy; regulation of mitophagy; SCF-dependent proteasomal ubiquitin-dependent protein catabolic process; ubiquitin-dependent protein catabolic process
Cellular component: mitochondrial intermembrane space; mitochondrial outer membrane; mitochondrion; nuclear speck; cytosol; ubiquitin ligase complex; cytoplasm; nucleus
Genetic constraint (gnomAD): Loss-of-function variants: 40 observed, 61.95 expected, observed/expected ratio (o/e) 0.65, 90% interval 0.5 to 0.84. The upper end of that interval is the gene's LOEUF score, 0.84, which puts it in group 3 of 6, group 1 being the genes least tolerant of losing a copy. Missense variants: 676 observed, 774.62 expected, observed/expected ratio (o/e) 0.87, 90% interval 0.82 to 0.93. Synonymous variants: 263 observed, 281.06 expected, observed/expected ratio (o/e) 0.94, 90% interval 0.85 to 1.04.
Gene-disease validity (ClinGen):
ClinGen rates the evidence that FBXL4 causes each of these diseases.
Leigh syndrome (autosomal recessive): Definitive. A progressive neurological disease defined by specific neuropathological features associating brainstem and basal ganglia lesions.
mitochondrial disease (autosomal recessive): Definitive.
Homologues: Orthologues: chimpanzee FBXL4 (99% identical), macaque FBXL4 (98% identical), dog FBXL4 (95% identical), pig FBXL4 (94% identical), rabbit FBXL4 (94% identical), mouse Fbxl4 (93% identical), rat Fbxl4 (93% identical), guinea pig FBXL4 (88% identical), tropical clawed frog fbxl4 (76% identical), zebrafish fbxl4 (68% identical), Drosophila melanogaster Fbxl4 (33% identical), Drosophila melanogaster CG12402 (20% identical), and 1 more. Paralogues in human: FBXL20 (15% identical), FBXL2 (15% identical), FBXL5 (14% identical), FBXL13 (14% identical), FBXL7 (14% identical), FBXL6 (14% identical), FBXL18 (13% identical), FBXL16 (13% identical), SKP2 (12% identical), FBXL17 (12% identical), FBXL14 (11% identical), FBXL19 (11% identical), and 3 more.
Diseases named in the same sentence as FBXL4 in open-access papers:
FBXL4 is named in the same sentence as 65 diseases in open-access papers, as found by Europe PMC text mining. Sharing a sentence is not in itself a finding about the gene and the disease. The quoted sentences say what the papers report.
mtDNA depletion syndrome (10 papers, 2016 to 2025). "Our results suggest that the increased basal mitophagy and associated molecular phenotypes in FBXL4‐associated mtDNA depletion syndrome are caused by NIX and BNIP3 hyperaccumulation." (PMID 37161784, 2023). "We propose that the dysregulation of NIX and BNIP3 turnover causes excessive basal mitophagy in FBXL4‐associated mtDNA depletion syndrome." (PMID 37161784, 2023). "Mutations in FBXL4 and C10orf2 causing mitochondrial DNA depletion syndrome were identified." (PMID 27391121, 2016). "FBXL4-MTDPS is a cerebral–muscular subtype of mtDNA depletion syndrome, characterized by hypotonia, lactic acidosis, and severe developmental delay." (PMID 41142849, 2025). "Analysis of an FBXL4 mutant, associated with mitochondrial DNA depletion syndrome 13, highlights the pathophysiological relevance of NIX as a substrate for FBXL4 and suggests a molecular explanation for the aetiology of the disease." (PMID 37102372, 2023).
lactic acidosis (5 papers, 2019 to 2025). Metabolic acidosis characterized by the accumulation of lactate in the body. "They had symptoms of encephalomyopathy, lactic acidosis and myocardial hypertrophy, which were consistent with the characteristics of mitochondrial injury myopathy caused by FBXL4 gene mutation." (PMID 35237671, 2021). "Biallelic variants in FBXL4 cause FBXL4-related mitochondrial DNA depletion syndrome (FBXL4-MTDPS), characterized by lactic acidosis and developmental delay." (PMID 41142849, 2025). "Indeed, elevated lactate levels in blood from patients with FBXL4–/– disease are a commonly observed indicator of extracellular lactate accumulation, clinically described as lactic acidemia and, when at sufficient levels to reduce blood pH, the cause of lactic acidosis." (PMID 35881484, 2022). "One of these FBXL4 (F-box and leucine-rich repeat protein 4) variants causes encephalomyopathic mtDNA depletion syndrome 13 (MTDPS13), which presents as a failure to thrive, severe global developmental delay, hypotonia, early infantile onset of encephalopathy, and lactic acidosis." (PMID 37822418, 2023). "Among those, FBXL4 mutations result in the encephalomyopathic mtDNA depletion syndrome 13 (MTDPS13; OMIM #615471), which commonly presents as a combination of failure to thrive, neurodevelopmental delays, encephalopathy, hypotonia, and persistent lactic acidosis." (PMID 30804983, 2019). "Mitochondrial DNA depletion syndrome 13 (MTDPS 13), also known as FBXL4-related encephalopathy, is a form of MDS manifested by early lactic acidosis, hypotonia, developmental delay, and feeding difficulty." (PMID 35237671, 2021).
prostate carcinoma (4 papers, 2017 to 2022). A carcinoma that arises from epithelial cells of the prostate gland. "The FBXL4 gene is identified as a potential tumor suppressor in prostate cancer, since the loss of FBXL4 has been correlated with advanced tumor stage and poor survival." (PMID 35625741, 2022). "Consistent with the association of FBXL4 loss with prostate cancer metastasis, we demonstrated that FBXL4 regulates cell motility and invasiveness by both, FBXL4 knockdown and overexpression." (PMID 28698647, 2017). "Further study revealed that FBXL4 was also deleted in a proportion of early stage prostate cancer cases, which was associated with poor prognosis and reduced survival." (PMID 28698647, 2017). "We demonstrated that loss of FBXL4 can be detected in prostate cancer CTCs, making it possible to analyse FBXL4 status in CTCs to monitor the risk of bone metastasis." (PMID 28698647, 2017). "More importantly, loss of FBXL4 was significantly associated with death from prostate cancer (HR 1.7, p = 0.009) by univariate analysis." (PMID 28698647, 2017). "Therefore, loss of FBXL4 in prostate cancer tissue, while significantly correlating with advanced disease, was not an independent prognostic factor for patient outcome." (PMID 28698647, 2017). "By analysing prostate cancer bone metastases using high density microarrays, we found a common genomic copy number loss at 6q16.1–16.2, containing the FBXL4 gene, which was confirmed in larger series of bone metastases by fluorescence in situ hybridisation (FISH)." (PMID 28698647, 2017). "To investigate if loss of FBXL4 genomic region also occurs at early stage of prostate cancer development, we analysed 145 primary cancer samples by FISH and detected FBXL4 genomic loss in 20 cases (13.8%), but not in any of the 55 BPH cases used as non-neoplastic controls." (PMID 28698647, 2017). "As loss of FBXL4 was found in prostate cancer bone metastases and about 95% of bone organic matter consists of collagen, we further analysed cell motility/invasion in the context of a bone microenvironment by seeding prostate cancer cells as a single cell suspension on top of collagen gels." (PMID 28698647, 2017). "FBXL4 is considered to participate in oxidative phosphorylation, mitochondrial dynamics, cell migration, prostate cancer metastasis, circadian GABAergic cyclic alteration, etc.." (PMID 32429265, 2020). "In vitro analysis showed that FBXL4 plays a role in regulating the migration and invasion of prostate cancer cells." (PMID 28698647, 2017). "Although the functional effect of FBXL4 on migration and invasion of prostate cancer cell lines in our study is low, FBXL4 downregulation consistently led to the increase while overexpression resulted in the decrease of cell migration and invasiveness." (PMID 28698647, 2017). "To functionally investigate how FBXL4 contributes to prostate cancer progression, we knocked it down with small interfering RNAs (siRNA) in DU145, 22RV1 and PC3 cells." (PMID 28698647, 2017). "FBXL4 knockdown increased Matrigel invasion in all prostate cancer cell lines (p = 0.001, 0.04 and 0.0001 for DU145, 22RV1 and PC3, respectively)." (PMID 28698647, 2017). "The relatively low frequency of FBXL4 genomic region loss in primary tumours and its significant increase in frequency in metastatic samples (p = 0.0003) further supports the hypothesis that FBXL4 is a gene that suppresses prostate cancer metastatic progression." (PMID 28698647, 2017). "Functional analysis of FBXL4 in prostate cancer cell lines suggested its involvement in cell migration and invasion, potentially through regulation of the levels of Endoplasmic Reticulum Lectin 1 (ERLEC1) protein, a regulator of cellular stress-response and promoter of metastatic cell survival." (PMID 28698647, 2017). "All these findings suggest that FBXL4 could be the putative TSG located at the deleted region, whose loss may result in prostate cancer progression." (PMID 28698647, 2017).
prostate carcinoma (continued). "Therefore, FBXL4 could be a potential novel prostate cancer suppressor gene, which may prevent cancer progression and metastasis through controlling cell invasion." (PMID 28698647, 2017). "However, changing FBXL4 expression level did not affect cell proliferation or protein levels of EMT markers that we examined, suggesting that FBXL4 may control proteins in different cellular pathways, which contribute to prostate cancer invasion and metastasis." (PMID 28698647, 2017). "By genomic profiling of prostate cancer bone metastatic samples, we found a common genomic deletion at 6q16.1–16.2 and through further investigations we identified the FBXL4 gene, located within this 6q16.1–16.2 region, as the putative TSG in regulating prostate cancer bone metastases." (PMID 28698647, 2017). "In our clinical samples, only FBXL4 but not BRN2 expression correlated with prostate cancer progression." (PMID 28698647, 2017).
Encephalopathy (3 papers, 2019 to 2023). Encephalopathy is a term that means brain disease, damage, or malfunction. "This work presents two patients with severe encephalopathy and severe mtDNA depletion in muscle associated with novel variants in FBXL4; S1 harboring two variants in compound heterozygosis c.[858+5G>C];[1510T>C] and S2 harboring one variant in homozygosis c.[851delC];[851delC]." (PMID 31969900, 2019).
mitochondrial DNA depletion syndrome 13 (3 papers, 2024 to 2025). Any mitochondrial DNA depletion syndrome in which the cause of the disease is a mutation in the FBXL4 gene. "Mutations in human FBXL4 cause mitochondrial DNA depletion syndrome 13 (MTDPS13) a severe pathology characterized by encephalopathy, stunted growth, and metabolic deficiencies." (PMID 38991726, 2024). "The post-translational regulation of BNIP3L and BNIP3 is disrupted in mitochondrial DNA depletion syndrome 13 (MTDPS13), a multisystem disorder disease caused by variations in the FBXL4 gene." (PMID 40352787, 2025). "The post-translational regulation of BNIP3L and BNIP3 is disrupted in mitochondrial DNA depletion syndrome 13 (MTDPS13), a multi-systemic disorder caused by mutations in the FBXL4 gene and characterized by elevated mitophagy and mitochondrial DNA/mtDNA depletion in patient fibroblasts." (PMID 38423516, 2024).
cardiac hypertrophy (2 papers, 2020 to 2026). "This study aimed to elucidate the role and underlying molecular mechanisms of an FBP, F-box and leucine-rich repeat protein 4 (FBXL4), in pathological cardiac hypertrophy." (PMID 41589689, 2026). "Restoration of FBXL4 expression via AAV9 delivery ameliorated cardiac hypertrophy and dysfunction in FBXL4-iCKO mice, while AAV9-mediated PFN1 knockdown or pharmacological inhibition partially reversed these phenotypes." (PMID 41589689, 2026).
heart failure (2 papers, 2025 to 2026). Inability of the heart to pump blood at an adequate rate to meet tissue metabolic requirements. "Transcriptomic analysis of murine heart failure and human dilated cardiomyopathy samples revealed consistent downregulation of FBXL4." (PMID 41589689, 2026). "Transfection of FBXL4 rescued the cardiac geometry and the mitochondrial integrity with altered mitochondrial dynamics in the adult mice model of the heart failure with preserved ejection fraction." (PMID 40556660, 2025).
mitochondrial encephalomyopathy (2 papers, 2014 to 2023). A heterogenous group of disorders characterized by alterations of mitochondrial metabolism that result in muscle and nervous system dysfunction. "In conclusion, we have made a mechanistic link between FBXL4 and NIX in setting the levels of basal mitophagy that can add to the molecular understanding of the aetiology of early‐onset mitochondrial encephalomyopathy." (PMID 37102372, 2023).
Brain atrophy (1 paper, 2022). Partial or complete wasting (loss) of brain tissue that was once present. "Under stressed conditions, several major morphological abnormalities developed, including brain atrophy and neurologic and/or muscular impairment, features reminiscent of those seen in patients with FBXL4-based mitochondrial disease." (PMID 35881484, 2022).
cardiomyopathy (1 paper, 2021). A disease of the heart muscle or myocardium proper. "FBXL4, ANT1, AGK, and SLC25A4 have been confirmed to be associated with cardiomyopathy." (PMID 35237671, 2021).
coenzyme Q10 deficiency (1 paper, 2025). A genetically heterogeneous condition, typically inherited in an autosomal recessive fashion, characterized by coenzyme Q10 deficiency. "An evaluation of body mass index (BMI) revealed mean BMI values of 16.49 ± 3.85 in patients with MELAS, 23.83 ± 11.47 in patients with CoQ10 deficiency, 11.98 ± 2.97 in Leigh syndrome, and 27.34 ± 15.37 in the FBXL4, LHON group." (PMID 41438888, 2025). "When genetic subtypes were analyzed, migraine headache was reported 100% in FBXL4 mutations, 88.9% in Coenzyme Q10 deficiency, 75% in Leigh syndrome, and 40% in MELAS." (PMID 41438888, 2025).
Cognitive decline (1 paper, 2025). "Cognitive decline was present in all patients (100%) with Leigh, FBXL4 mutations and LHON." (PMID 41438888, 2025).
depression (1 paper, 2020). "The SNP associated with depression (rs12202410) was near the F-box and leucine-rich repeat protein 4 (FBXL4) gene which is related to energy homoeostasis." (PMID 31576797, 2020).
MELAS (1 paper, 2025). "Decreased muscle mass was significantly observed in patients with MELAS, FBXL4." (PMID 41438888, 2025).
metastatic cancers (1 paper, 2017). A carcinoma which has spread from the original site of growth to another anatomic site. "We also demonstrated that FBXL4 was not only commonly deleted in bone metastasis samples but also in early stage cancers, although at significantly lower frequency than in the metastatic cancers." (PMID 28698647, 2017).
Mitochondrial encephalopathy (1 paper, 2022). "FBXL4 has a crucial function in development, metabolism, and mitochondrial dynamics and may be used to develop novel therapies for mitochondrial encephalopathy." (PMID 36032143, 2022).
pneumonia (1 paper, 2025). An acute, acute and chronic, or chronic inflammation focally or diffusely affecting the lung parenchyma, caused by an infection in one or both of the lungs (by bacteria, viruses, fungi, or mycoplasma.). "This study reports the cases of two brothers with a novel FBXL4 variant who died of fulminant pneumonia." (PMID 41142849, 2025). "FBXL4-MTDPS may involve intrinsic defects in pulmonary infection defense, increasing susceptibility to fatal infection such as pneumonia." (PMID 41142849, 2025).
Supraventricular tachycardia (1 paper, 2021). Supraventricular tachycardia (SVT) is an abnormally increased heart rate (over 100 beats per minute at rest) with origin above the level of the ventricles. "Seven of the nine patients (77%) with FBXL4 deficiency showed abnormal cardiac manifestations, including fallot syndrome (TOF), supraventricular tachycardia (SVT), ventricular septal defect (ASD), and left or right ventricular hypertrophy." (PMID 35237671, 2021).
mitochondrial disease (6 papers, 2020 to 2025). "In contrast to PARKIN, FBXL4 and its downstream targets thus provide an important example of a clinically relevant mitophagy pathway whose impairment causes severe mitochondrial disease." (PMID 38684669, 2024). "The SCFFBXL4 ubiquitin ligase complex suppresses mitophagy by controlling the degradation of BNIP3 and NIX mitophagy receptors, and FBXL4 mutations result in mitochondrial disease as a consequence of elevated mitophagy." (PMID 38992176, 2024). "Forty-eight FBXL4 pathogenic variants have been reported in 94 patients, making it one of the more common nuclear gene causes of primary mitochondrial disease." (PMID 35881484, 2022). "Taken together, the results we present here show that FBXL4 prevents mitochondrial removal via autophagy and that loss of FBXL4 leads to decreased mitochondrial content and mitochondrial disease." (PMID 32525278, 2020). "Here, we describe an Fbxl4 knockout mouse and show that it recapitulates important phenotypes present in patients with mitochondrial disease caused by FBXL4 mutations." (PMID 32525278, 2020). "Neuromuscular dysfunction is a hallmark symptom of human FBXL4–/– mitochondrial disease." (PMID 35881484, 2022). "FBXL4 mutations are found in ~ 0.7% of all mitochondrial patients and in ~ 14% of children with congenital lactic acidosis, making it one of the most common causes of mitochondrial disease." (PMID 32525278, 2020). "Despite the potential relevance of studying FBXL4 mitochondrial disease in mammals, the homozygous Fbxl4-knockout mouse model showed perinatal lethality, with low survival rate." (PMID 35881484, 2022). "Since FBXL4 dysfunction leads to an increase in mitochondrial fissioning and subsequent autophagy this suggests that the autophagic pathway is a major vulnerability of mitochondrial disease etiology." (PMID 40110048, 2025). "Here, we characterized what we believe to be novel genetic models of FBXL4–/– mitochondrial disease and evaluated the preclinical efficacy of DCA as a candidate therapy across 3 evolutionarily distinct model species, namely C. elegans, zebrafish, and human fibroblasts." (PMID 35881484, 2022). "Therefore, we performed a range of quantitative assessments to determine whether fbxl-1(ok3741) mutant worms recapitulated the impaired neuromuscular activity typical of FBXL4–/–-based mitochondrial disease." (PMID 35881484, 2022).
tumor (5 papers, 2015 to 2023). "Loss of FBXL4 gene is associated with advanced tumor stage and poor survival in prostate cancer." (PMID 32226545, 2020). "We also demonstrated that FBXL4 deletion is detectable in circulating tumour cells (CTCs), making it a potential prognostic biomarker by ‘liquid biopsy’." (PMID 28698647, 2017). "In this context, one interesting link between FBXL4 and VHL has been made in a genome‐wide CRISPR screen for synthetic lethality with common tumour suppressors." (PMID 37102372, 2023).